FANCD2OS (FANCD2 opposite strand)
Description:
Reduces testosterone levels by inhibiting steroidogenic enzymes and by promoting apoptosis in Leydig cells.
Synonyms: C3orf24; MGC40179
Tractability: No criterion of Open Targets' tractability assessment is met for any kind of drug.
Gene: Protein-coding gene on chromosome 3 (10,081,317 to 10,108,255, reverse strand). Ensembl gene ENSG00000163705.
Subcellular location: Cytoplasm
Subcellular location (Human Protein Atlas): Vesicles
Gene Ontology:
Biological process: negative regulation of testosterone biosynthetic process
Cellular component: cytoplasm
Genetic constraint (gnomAD): Loss-of-function variants: 11 observed, 14.07 expected, observed/expected ratio (o/e) 0.78, 90% interval 0.49 to 1.29. The upper end of that interval is the gene's LOEUF score, 1.29, which puts it in group 5 of 6, group 1 being the genes least tolerant of losing a copy. Missense variants: 217 observed, 225.11 expected, observed/expected ratio (o/e) 0.96, 90% interval 0.86 to 1.08. Synonymous variants: 69 observed, 88.54 expected, observed/expected ratio (o/e) 0.78, 90% interval 0.64 to 0.95.
Homologues: Orthologues: chimpanzee FANCD2OS (100% identical), macaque FANCD2OS (99% identical), dog FANCD2OS (96% identical), pig FANCD2OS (96% identical), rabbit FANCD2OS (96% identical), guinea pig FANCD2OS (93% identical), rat Fancd2os (93% identical), mouse Fancd2os (92% identical), rat Fancd2osl1 (70% identical), tropical clawed frog fancd2os (51% identical).